SMAD4 (SMAD family member 4)
Diseases named in the same sentence as SMAD4 in open-access papers (continued):
Sharing a sentence is not in itself a finding about the gene and the disease.
head and neck squamous cell carcinoma (16 papers, 2011 to 2024). A squamous cell carcinoma that arises from any of the following anatomic sites: lip and oral cavity, nasal cavity, paranasal sinuses, pharynx, larynx, and salivary glands. "Further, SMAD2 and SMAD4 as the two essential components of the TGF beta-Smad signaling pathway also have such variant pattern contributing to the tumorigenesis of head and neck squamous cell carcinoma in contrast with other tumor types." (PMID 34513841, 2021). "Of note, loss of SMAD4 increases genomic instability and appears to contribute to the emergence of head and neck squamous cell carcinoma (HNSCC), which is a tumor that is frequently encountered in FA patients." (PMID 21826217, 2011). "In addition to EGFR, the rate of Smads mutations is also low in OSCC tissues, although current evidence suggests that the deletion of Smad4 contributes to the metastasis of head and neck squamous cell carcinoma (HNSCC)." (PMID 30914776, 2019). "DRAK1 can interrupt the formation of the Smad3/Smad4 complex by binding to Smad3, a process that inhibits TGF-β tumor suppressor signaling in head and neck squamous cell carcinoma (HNSCC) and increases tumor activity." (PMID 36386181, 2022). "Although mutation and homozygous deletion of SMAD4 were rare in head and neck squamous cell carcinoma (HNSCC), knockout SMAD4 could lead to spontaneous oral squamous cell carcinoma development in an animal model, suggesting the tumor suppressor role of SMAD4 in oral tumorigenesis." (PMID 23826135, 2013). "SMAD4 is the most common SMAD family protein disrupted in cancers, and its functional loss or repression has been reported at high frequencies in pancreatic cancer, head and neck squamous cell carcinoma (HNSCC), and CRC, as well as in biliary, bladder, breast, liver, lung, and esophageal cancers." (PMID 33834163, 2019). "The same study demonstrated a correlation of SMAD4 knockdown with the downregulation of BRCA1 and RAD51 protein expression in head and neck squamous cell carcinoma (HNSCC) as well as increased expression of TβR1 and phospho-SMAD3." (PMID 33418880, 2021). "However, in Head and neck squamous cell carcinoma (HNSCC) cell lines, where DRAK1 is overexpressed, DRAK1 in the cytoplasm binds to Smad3 and sequesters it in the cytoplasm, thereby preventing Smad3/Smad4 complex formation and inhibiting TGF-β1 tumor suppression." (PMID 31330998, 2019).
polyposis (16 papers, 2013 to 2026). "Today, most genetic analyses are done with a next generation sequencing (NGS) panel comprising several polyposis-associated genes (including SMAD4 and APC)." (PMID 39039610, 2024). "As frequent alterations, missense mutations are presumably selected during tumorigenesis and polyposis due to their structural impacts on SMAD4 functions and TGF-ß signaling pathway." (PMID 35154600, 2021). "Concerning JPS, surveillance often starts at 12–15 years of age and is repeated every 1–3 years depending on the severity of polyposis, though recent guidelines differentiate between the genetic subtypes as patients with a pathogenic variant in SMAD4 have a more severe gastric phenotype." (PMID 39039610, 2024). "In this regard, it is worth noting that the characterization of the molecular effects of SMAD4 splicing variants may support the clinical diagnosis and management of patients with a personal and/or family history of cancer and/or polyposis." (PMID 39063183, 2024). "Additionally, patients with SMAD4-related JPS have a more severe gastric phenotype including increased risk of massive polyposis, GC, and characteristic endoscopic features of the gastric mucosa." (PMID 37354305, 2023). "Our results reveal a significant increase in intestinal polyps in Smad4 knock-out mice across the entire population, emphasizing the broad influence of Smad4 on polyposis." (PMID 38891999, 2024). "Our findings revealed a significant increase in intestinal polyps in Smad4 knock-out mice across the entire population, emphasizing the broad influence of Smad4 on polyposis." (PMID 38891999, 2024). "All these facts make the p.Q82* of the NTHL1 gene screening reasonable in polyposis patients (especially in an unusual disease course), with APC, MUTYH, STK11, BMPR1A, and SMAD4 mutations excluded." (PMID 37834005, 2023). "Here, we demonstrate that Alk3 or Smad4 KO in Gli1+ cells results in tumefaction, cavity formation, and polyposis development in the large intestine." (PMID 37889976, 2023). "In the Smad4+/− group, 64% had remarkable polyposis in the colon, 45% had signs of bowel obstruction, and 45% had bloody feces, consistent with large polyps." (PMID 37296966, 2023). "In general, we observed that the clinical spectrum of patients with a PV in SMAD4 or BMPR1A was very wide: from massive polyposis (both gastric and colorectal) to very few colorectal polyps." (PMID 37354305, 2023). "On the contrary, neither the SMAD4 nor the 2 monoallelic MUTYH mutation carriers showed any sign of polyposis to our knowledge." (PMID 30256826, 2018). "It seems as if patients with mutations in APC, BMPR1A, SMAD4 and GREM1 can have similar polyposis phenotypes but carriers of GREM1 mutation with HMPS might not have the same risk for extra-colonic disease as patients with BMPR1A mutations and HMPS." (PMID 27696107, 2017). "Given the earlier studies on the importance of SMAD4 integrity and considering the prevalence of CRC in Iran, this study was designed to evaluate the contribution of SMAD4 mutations in colorectal carcinogenesis and polyposis and their correlation with clinicopathological aspects." (PMID 35154600, 2021). "Among all the non-MMR genes, APC, MUTYH and SMAD4 are well known to be implicated in CRC, specifically in polyposis." (PMID 30256826, 2018). "Our ultimate goal is to enable an appropriate approach to prophylactic strategies in Polish families with polyposis, especially in those patients whose APC, MUTYH, STK11, BMPR1A, and SMAD4 gene testing showed no abnormalities." (PMID 37834005, 2023).
head and neck cancer (15 papers, 2016 to 2024). A primary or metastatic malignant neoplasm affecting the head and neck. "Another study on head and neck cancer reported that loss of SMAD4 was associated with increased TGF β 1 activity." (PMID 33902690, 2021). "For example, PARPi was found effective in head and neck cancer with SMAD4-deficiency." (PMID 35071239, 2021). "The gene analysis that we performed may support the identification of SMAD4 mutations as a diagnostic marker or even as a potential therapeutic target in head and neck cancer." (PMID 31867281, 2019). "Furthermore, loss of SMAD4 causes head and neck cancer in mice and promotes metastasis in human pancreatic cancer." (PMID 28638102, 2017). "More recently, studies in the Smad4 conditional knockout mice that develop head and neck cancers, demonstrate a key role for Smad4 as a guardian of the genome through regulation of the Fanconi anemia/Brca (Fanc/Brca) DNA repair pathway." (PMID 29234487, 2017). "Recent studies of Smad4 knockout mice, that develop head and neck cancers, demonstrated a significant role for Smad4 in promoting genomic stability through regulation of the Fanconi anemia/BRCA DNA repair pathway." (PMID 27248179, 2016). "Similarly, SMAD4 conditional knockout mice with head and neck cancer, revealed a role for SMAD4 in the regulation of the Fanconi anemia/BRCA DNA repair pathway, also suggesting an involvement in genomic stability." (PMID 33418880, 2021). "Therefore, the proposed analysis of the genetic status may facilitate the identification of mutations in the SMAD4 gene as a novel diagnostic marker or therapeutic target in HNSCC and other head and neck cancers." (PMID 31867281, 2019). "This is very prominent in squamous cell carcinoma of the skin and of the Head and Neck cancer (HNSCC or HNC) and suggests a distinct role of SMAD4 in the progression of various types of tumours." (PMID 35144669, 2022).
breast tumors (14 papers, 2011 to 2024). "Alterations of Smad4 gene were reported in pancreatic, colorectal, gastric, esophageal, and breast tumors; its loss is associated with tumorigenesis and progression." (PMID 25890228, 2015). "Indeed, SMAD2 and SMAD4 are closely linked on chromosome 18q21, and therefore, in most breast tumors where one gene shows hemizygous loss, the other is also reduced to hemizygosity." (PMID 34475389, 2021). "A report that seems to partially address this concern from Wu and colleagues revealed that OVOL2 thwarts TGF-β signalling and blocks EMT during breast tumour metastasis by repressing SMAD4 expression and interfering with SMAD4 and SMAD2/3 complex formation." (PMID 34868979, 2021). "At least 15% of breast tumors exhibit LOH at the 18q21 locus on which SMAD4 is situated and breakpoints in this region are associated with minimum copy number suggesting a tumor suppressor role." (PMID 21835029, 2011). "Using publically available online tissue expression data, SMAD3 and SMAD4 expression in breast tumors versus normal breast tissue were assessed using two independent samples t-test and Levin's test for the equality of variance." (PMID 21835029, 2011). "TrkB is capable of binding to SMAD2, SMAD3, and SMAD4 in TrkB-expressing human breast tumors." (PMID 32340410, 2020). "To assess the requirement for SMAD4 in BMP4-mediated suppression of metastasis, we knocked down SMAD4 in two different breast tumors and enforced SMAD4 expression in a third line with endogenous SMAD4 deletion." (PMID 38689334, 2024). "Sirt7 overexpression suppresses S-phase kinase-associated protein 2 (Skp2)-Culin1-F-box (SCF) E3 ligase-mediated AKT ubiquitination and TGF-β/SMAD family member 4 (SMAD4) signaling, thus antagonizing the growth of breast tumors and metastasis to distal organs." (PMID 37676263, 2024). "In addition, the expression levels of p-Smad2, p-Smad3, and Smad4 in the nucleus of MCF-7 breast tumor cells were measured by immunofluorescence microscopy, and we found that SSA could reduce the level of p-Smad2/3 in the nucleus with or without the presence of TGFβ1." (PMID 26769851, 2016). "In contrast, Aspirin was reported to inhibit breast tumor cell growth, EMT and migration via the TGF-β/SMAD4 signaling pathway; and to exert anti-tumor effects through other pathways such as the cyclooxygenase (COX) pathway and the NF-ĸB pathway in various cancers." (PMID 31824307, 2019). "Finally, we constructed a signature comprising genes that were specifically regulated by BMP4 in the absence of SMAD4 and found that this signature is increasingly represented in high-grade breast tumors and predicts significantly worse overall survival in the Metabric patient dataset." (PMID 38689334, 2024).
colitis (14 papers, 2018 to 2025). Inflammation of the colon. "We evaluated mucosal healing in an acute dextran sulfate sodium mouse model that shows an alleviated colitis response after epithelial-specific loss of Smad4." (PMID 39366762, 2024). "Our results revealed that S100A4+ cell-specific Smad4 deficiency aggravates the transformation of colitis into CRC by promoting the infiltration of macrophages and inflammatory factors." (PMID 39664586, 2024). "Smad4 deficiency in S100A4+ cells exacerbated DSS-induced colitis and promoted colorectal tumorigenesis." (PMID 39664586, 2024). "We find that the epithelial-specific loss of Smad4 has a protective effect against the colitis response in the acute DSS model." (PMID 39366762, 2024). "S100A4+ macrophage-specific Smad4 deletion enhances colitis-associated tumorigenesis by promoting macrophage lipid metabolism-dependent M2 polarization, thereby revealing Smad4 in S1000A4+ macrophages as a potential prognostic marker for CRC patients." (PMID 39664586, 2024). "We found that S100A4+ cell-specific Smad4 deletion aggravated DSS-induced colitis and enhanced AOM/DSS-induced colitis-associated tumorigenesis." (PMID 39664586, 2024). "Previous studies used haploinsufficiency or partial deletion of Smad4 in the epithelium and showed that Smad4 loss promotes colitis and colitis-associated cancer." (PMID 39366762, 2024). "Smad4 loss in intestinal epithelium aggravates colitis and colitis‐associated neoplasia induced by dextran sulfate sodium (DSS) and azoxymethane/dextran sulfate sodium (AOM/DSS), leading to over‐activated immune responses and increased TGF‐β1 levels." (PMID 37261975, 2023). "To uncover the molecular mechanism underlying the observed effects of TGF‐β/Smad4 on colitis and CAC, we interrogated the available gene expression of the colonic tissues from CD and UC patients." (PMID 37261975, 2023). "Attenuation of YAP/TAZ prevents TGF‐β1‐induced spheroid formation in Smad4−/– organoids and alleviates colitis and colitis‐associated cancer in Smad4‐deficient mice." (PMID 37261975, 2023). "Thus, the homeostatic responses and the enrichment of the regenerative gene signatures in the epithelium suggest that Smad4 loss has a protective effect against the DSS-induced colitis response." (PMID 39366762, 2024). "Furthermore, we detected upregulated expression of F4/80 and IFN‐γ in inflammatory areas in Smad4‐deficient mice, which possibly reflects the early inflammatory environment of colitis in Smad4‐deficient mice." (PMID 37261975, 2023). "Besides, the colon exhibited less disrupted patterning of the tight junction protein ZO‐1, and goblet cells were recovered, indicating that reduced expression of YAP/TAZ compensates the deteriorating effect of Smad4 deficiency in colitis." (PMID 37261975, 2023). "Notably, deletion of Smad4 in the untransformed intestinal epithelium elicits a pronounced TNF-mediated inflammatory response that is sufficient to drive colitis-associated carcinomas." (PMID 33673710, 2021). "However, it remains unclear whether Smad4 in S100A4+ cells affects colitis-associated carcinogenesis." (PMID 39664586, 2024). "Deficiency of Smad4 in the colon epithelium increases CCL20 expression and chemoattraction of CCR6+ immune cells, thus promoting colitis-associated carcinogenesis." (PMID 39664586, 2024). "A histological assessment revealed a significant upregulation of S100A4 expression and down-regulation of Smad4 in both colitis and CRC tissues." (PMID 39664586, 2024). "Smad4 deletion in epithelial cells aggravates DSS-induced colitis and AOM/DSS induced-colon tumorigenesis." (PMID 39664586, 2024).
colitis (continued). "Alleviated fibrotic response in the Smad4 knockout mouse model of acute colitis parallels the epithelial-specific extracellular matrix changes and regenerative response in the intestinal epithelium." (PMID 39366762, 2024). "In summary, our work demonstrates a potential link between the epithelial Smad4 status and aberrant immune responses in the intestine and highlights an epithelial‐intrinsic role of TGF‐β/Smad4 in colitis and CAC." (PMID 37261975, 2023). "In this study, we show that Smad4 deletion in mouse intestinal epithelium promotes intestinal inflammation and hyperplasia in chemically induced colitis and CAC." (PMID 37261975, 2023). "Taken together, these results indicate that Smad4 plays a critical role in attenuating colitis development in an epithelial cell‐autonomous manner." (PMID 37261975, 2023). "We found that loss of Smad4 in intestinal epithelial cells increases TGF‐β1 expression and lead to exacerbated colitis and CAC in mouse models." (PMID 37261975, 2023). "Recent research on DSS-induced colitis found that expression patterns were associated with disease progression; specifically, BMP4 and Smad4 expression in the crypt was upregulated during early-stage DSS-induced colitis and downregulated during the late stage." (PMID 37391444, 2023). "We first assessed the effect of SMAD4 overexpression on colitis and found that the body weight of Htr2bΔIEC; Smad4OE/+ mice recovered compared with Htr2bΔIEC mice." (PMID 35664068, 2022). "Our results showed that BMP4 and SMAD4 were downregulated at the late stage of DSS-induced colitis, which is consistent with other studies we examined." (PMID 34692671, 2021). "Of note, Smad4+/− mice are more prone to develop acute inflammation as seen in a chemically-induced colitis model." (PMID 29977289, 2018). "Taken together, our findings revealed the cell-specific role of Smad4 in colitis and CAC." (PMID 39664586, 2024). "Although Smad4 loss alone in the intestinal epithelium does not affect the gross phenotype, it increases colitis-associated cancer in the chronic DSS mouse model." (PMID 39366762, 2024). "Smad4 expression in S100A4+ cells was also decreased in colitis and tumor tissues." (PMID 39664586, 2024). "Similarly, our results supported this conclusion and demonstrated that S100A4+ cell-specific Smad4 ablation aggravated colitis and CRC." (PMID 39664586, 2024). "Collectively, our results uncover a novel mechanism in which Smad4‐independent TGF‐β signaling mediates colitis and CAC development via YAP and may provide therapeutic insights into the treatment of these gastrointestinal diseases." (PMID 37261975, 2023). "We therefore examined whether immune responses were perturbed in Smad4‐deficeint mice subject to DSS‐induced colitis." (PMID 37261975, 2023). "Notably, severer colitis phenotypes, characterized by relatively more body weight loss, short colon, and higher clinical disease activity index (DAI) score, were observed in Smad4‐deficient mice." (PMID 37261975, 2023). "These tumours strongly resemble human SMAD4-deficient ulcerative colitis-associated CRCs, thus implicating TGFβ/BMP signalling in the suppression of the innate immune mechanisms that become derailed in colitis." (PMID 33673710, 2021). "SMAD4 may play an important role in the pathogenesis of IBD as indicated in experimental models of colitis." (PMID 29977289, 2018). "Notably, there was an increase in the proportion of infiltrated immune cells (CD45+), CD4+ and CD8+ T cells, macrophages (CD11b+F4/80+), and neutrophils (CD11b+Gr1+) in Smad4−/− mice during colitis compared with those in WT mice, which was accompanied by enhanced IFNγ levels." (PMID 37261975, 2023). "We next challenged Smad4 conditional knockout mice and WT littermates with 3.5% DSS, a chemical drug that can induces experimental colitis." (PMID 37261975, 2023).